FYN (FYN proto-oncogene, Src family tyrosine kinase)
Description:
Non-receptor tyrosine-protein kinase that plays a role in many biological processes including regulation of cell growth and survival, cell adhesion, integrin-mediated signaling, cytoskeletal remodeling, cell motility, immune response and axon guidance. Inactive FYN is phosphorylated on its C-terminal tail within the catalytic domain. Following activation by PKA, the protein subsequently associates with PTK2/FAK1, allowing PTK2/FAK1 phosphorylation, activation and targeting to focal adhesions. Involved in the regulation of cell adhesion and motility through phosphorylation of CTNNB1 (beta-catenin) and CTNND1 (delta-catenin). Regulates cytoskeletal remodeling by phosphorylating several proteins including the actin regulator WAS and the microtubule-associated proteins MAP2 and MAPT. Promotes cell survival by phosphorylating AGAP2/PIKE-A and preventing its apoptotic cleavage. Participates in signal transduction pathways that regulate the integrity of the glomerular slit diaphragm (an essential part of the glomerular filter of the kidney) by phosphorylating several slit diaphragm components including NPHS1, KIRREL1 and TRPC6. Plays a role in neural processes by phosphorylating DPYSL2, a multifunctional adapter protein within the central nervous system, ARHGAP32, a regulator for Rho family GTPases implicated in various neural functions, and SNCA, a small pre-synaptic protein. Involved in reelin signaling by mediating phosphorylation of DAB1 following reelin (RELN)- binding to its receptor (By similarity). Participates in the downstream signaling pathways that lead to T-cell differentiation and proliferation following T-cell receptor (TCR) stimulation. Phosphorylates PTK2B/PYK2 in response to T-cell receptor activation. Also participates in negative feedback regulation of TCR signaling through phosphorylation of PAG1 and PDCD1. Phosphorylation of PAG1 promotes interaction between PAG1 and CSK and recruitment of CSK to lipid rafts. Phosphorylation of PDCD1 leads to the recruitment of PTPN11/SHP-2 that mediates dephosphorylation of key TCR proximal signaling molecules. CSK maintains LCK and FYN in an inactive form (By similarity). Promotes CD28-induced phosphorylation of VAV1. In mast cells, phosphorylates CLNK after activation of immunoglobulin epsilon receptor signaling (By similarity). Can also promote CD244-mediated NK cell activation.
Synonyms: SLK; SYN; MGC45350; p59-FYN
Tractability: Small molecule: an approved drug acts on it; a structure with a bound ligand is known; a high-quality ligand is known; it has a binding pocket of medium quality; it belongs to a druggable protein family. Antibody: UniProt places it where antibodies can reach, with high confidence; its Gene Ontology location is reachable by antibodies, with high confidence; the Human Protein Atlas places it where antibodies can reach. PROTAC: it is named in the literature on targeted protein degradation; ubiquitination databases record sites on it; its protein half-life has been measured; a small molecule that binds it is known.
Target class: Kinase; TK protein kinase group; Enzyme; Protein Kinase; Tyrosine protein kinase Src family
Chemical probes: SU6656
Gene: Protein-coding gene on chromosome 6 (111,660,332 to 111,873,475, reverse strand). Ensembl gene ENSG00000010810.
Subcellular location: Cytoplasm; Nucleus; Cell membrane; Perikaryon
Subcellular location (Human Protein Atlas): Plasma membrane; Cytosol
Pathways (Reactome):
Immune System: Antigen activates B Cell Receptor (BCR) leading to generation of second messengers; CD209 (DC-SIGN) signaling; CD28 dependent PI3K/Akt signaling; CD28 dependent Vav1 pathway; Co-inhibition by CTLA4; Co-stimulation by CD28; DAP12 signaling; Dectin-2 family; FCGR activation; FLT3 signaling through SRC family kinases; Regulation of signaling by CBL; Role of LAT2/NTAL/LAB on calcium mobilization; Signaling by CSF1 (M-CSF) in myeloid cells
Developmental Biology: CRMPs in Sema3A signaling; DCC mediated attractive signaling; EPH-Ephrin signaling; EPH-ephrin mediated repulsion of cells; EPHA-mediated growth cone collapse; EPHB-mediated forward signaling; Ephrin signaling; NCAM signaling for neurite out-growth; Reelin signalling pathway; SEMA3A-Plexin repulsion signaling by inhibiting Integrin adhesion; Sema3A PAK dependent Axon repulsion
Signal Transduction: Activated NTRK2 signals through FYN; NTRK2 activates RAC1; PI5P, PP2A and IER3 Regulate PI3K/AKT Signaling; PIP3 activates AKT signaling; RAF/MAP kinase cascade; Regulation of KIT signaling; Signaling by ERBB2; Signaling by SCF-KIT; VEGFA-VEGFR2 Pathway
Disease: Constitutive Signaling by Aberrant PI3K in Cancer; FCGR3A-mediated IL10 synthesis; FCGR3A-mediated phagocytosis; Nef and signal transduction; Signaling by phosphorylated juxtamembrane, extracellular and kinase domain KIT mutants
Hemostasis: Cell surface interactions at the vascular wall; GPVI-mediated activation cascade
and 5 more pathways
Gene Ontology:
Molecular function: disordered domain specific binding; enzyme binding; ephrin receptor binding; G protein-coupled receptor binding; growth factor receptor binding; identical protein binding; non-membrane spanning protein tyrosine kinase activity; phospholipase activator activity; phospholipase binding; protein binding; protein tyrosine kinase activity; scaffold protein binding; alpha-tubulin binding; signaling receptor binding; tau protein binding; tau-protein kinase activity; type 5 metabotropic glutamate receptor binding; ATP binding; CD4 receptor binding; CD8 receptor binding; peptide hormone receptor binding; phosphatidylinositol 3-kinase binding; protein kinase activity; protein-containing complex binding; T cell receptor binding; and 2 more
Biological process: cellular response to amyloid-beta; G protein-coupled glutamate receptor signaling pathway; heart process; intracellular signal transduction; natural killer cell activation; negative regulation of T cell activation; negative regulation of T cell receptor signaling pathway; T cell receptor signaling pathway; axon guidance; calcium ion transport; cell differentiation; cell surface receptor protein tyrosine kinase signaling pathway; cellular response to glycine; cellular response to hydrogen peroxide; cellular response to L-glutamate; dendritic spine maintenance; ephrin receptor signaling pathway; Fc-gamma receptor signaling pathway involved in phagocytosis; feeding behavior; learning; leukocyte migration; negative regulation of dendritic spine maintenance; negative regulation of hydrogen peroxide biosynthetic process; negative regulation of inflammatory response to antigenic stimulus; negative regulation of oxidative stress-induced intrinsic apoptotic signaling pathway; and 22 more
Cellular component: cytoplasm; cytosol; dendrite; endosome; membrane raft; nucleus; plasma membrane; cell body; glial cell projection; mitochondrion; perikaryon; perinuclear endoplasmic reticulum; perinuclear region of cytoplasm; postsynaptic density; actin filament; cell periphery; glutamatergic synapse; postsynaptic density, intracellular component; Schaffer collateral - CA1 synapse
Genetic constraint (gnomAD): Loss-of-function variants: 7 observed, 61.18 expected, observed/expected ratio (o/e) 0.11, 90% interval 0.064 to 0.22. The upper end of that interval is the gene's LOEUF score, 0.22, which puts it in group 1 of 6, group 1 being the genes least tolerant of losing a copy. Missense variants: 308 observed, 683.08 expected, observed/expected ratio (o/e) 0.45, 90% interval 0.41 to 0.5. Synonymous variants: 230 observed, 256.47 expected, observed/expected ratio (o/e) 0.9, 90% interval 0.8 to 1.
Homologues: Orthologues: chimpanzee FYN (100% identical), macaque FYN (100% identical), rabbit FYN (100% identical), dog FYN (99% identical), guinea pig FYN (99% identical), rat Fyn (99% identical), mouse Fyn (99% identical), pig FYN (99% identical), tropical clawed frog fyn (97% identical), zebrafish fyna (92% identical), zebrafish fynb (92% identical). Paralogues in human: YES1 (74% identical), FGR (71% identical), SRC (69% identical), HCK (57% identical), LYN (55% identical), LCK (54% identical), BLK (54% identical), FRK (47% identical), ABL2 (40% identical), ABL1 (39% identical), PTK6 (37% identical), SRMS (37% identical), and 20 more.
Diseases named in the same sentence as FYN in open-access papers:
FYN is named in the same sentence as 143 diseases in open-access papers, as found by Europe PMC text mining. Sharing a sentence is not in itself a finding about the gene and the disease. The quoted sentences say what the papers report.
breast carcinoma (26 papers, 2014 to 2025). "FYN causes tamoxifen resistance in breast cancer (ER+), and knockdown of FYN expression or use of FYN inhibitors significantly inhibits the growth of tamoxifen-resistant cells and the association with poor prognosis in breast cancer." (PMID 36740671, 2023). "The FYN protein is also associated with breast cancer chemotherapy drug sensitivity." (PMID 33456463, 2020). "A systematic analysis of miRNA-mediated gene regulation in tamoxifen-resistant breast cancer cell lines (TamRs) compared to their parental tamoxifen-sensitive cell lines demonstrated that miR-33b, miR-342-5p were significantly associated with FYN and can directly regulate its expression." (PMID 36740671, 2023). "Here we found that CLDN6 promotes the NRF2 nuclear export to induce ferroptosis by the AKT/GSK3β/FYN axis in breast cancer cells." (PMID 39984471, 2025). "FYN is highly expressed in many types of cancer such as glioblastoma, melanoma, squamous cell carcinoma, breast cancer, prostate cancer and PDAC." (PMID 40741875, 2025). "In breast cancer cells, FYN knockdown led to reduced phosphorylation of zeta/delta (Thr232) and Cdc25A (Ser124)." (PMID 36740671, 2023). "FYN upregulates the expression of mesenchymal markers of breast cancer, epithelial-mesenchymal transition (EMT)-related transcription factors, and downregulates the expression of epithelial cells to induce the development of EMT." (PMID 36740671, 2023). "The overexpression of FYN in breast cancer has been documented, and thus the proliferative phenotype of breast cancer disappears upon inhibition of FYN expression, suggesting that FYN is a downstream molecule of PTPN23 mediating breast carcinogenesis." (PMID 36740671, 2023). "FYN has been studied in prostate cancer, pancreatic cancer, leukemia, breast cancer, thyroid cancer, bile duct cancer, and other tumors." (PMID 36740671, 2023). "It has been demonstrated that FYN enhances NOTCH2 activation in basal breast cancer cells through STAT5-mediated upregulation of Jagged-1 and DLL4 NOTCH ligands, thereby contributing to the mesenchymal phenotype." (PMID 36740671, 2023). "FYN is required to maintain the basal breast cancer subtype, which is the most aggressive and has mesenchymal features with high metastatic capacity." (PMID 36740671, 2023). "The miR-381 inhibits MAPK signaling by downregulating FYN, thereby making breast cancer cells more sensitive to doxorubicin (DOX)." (PMID 36740671, 2023). "Overexpression of FYN in breast cancer has been reported in the literature, and FYN overexpression promotes cell proliferation, migration, and invasion." (PMID 36740671, 2023). "In breast cancer, the Ras oncogene significantly upregulates FYN mRNA, protein, and kinase activity." (PMID 36740671, 2023). "FYN can also promote the biosynthesis of miR-5088-5p by inducing its hypermethylation to mediate breast cancer proliferation and metastasis." (PMID 36740671, 2023). "It has been demonstrated that FYN promotes the proliferation and metastasis of oral cancer, colorectal cancer, breast cancer, lung cancer, pancreatic cancer, cholangiocarcinoma." (PMID 37016377, 2023). "miR-381 promotes the chemosensitivity of breast cancer cells to DOX by downregulating FYN to inactivate MAPK signaling." (PMID 36740671, 2023). "FYN is an important molecular marker in breast cancer that can serve as a predictor of early recurrence." (PMID 35453806, 2022). "An earlier study conducted on breast cancer cells (MCF-7) found that FYN gene expression was higher at 24 h." (PMID 32993565, 2020). "FYN was reported to be correlated with cell motility and proliferation and over-expressed in chronic myeloid leukemia, breast cancer, squamous head and neck carcinoma, and melanoma." (PMID 32933107, 2020). "Researchers have also revealed a prospective strategy to better manage breast cancer by targeting FYN." (PMID 31285693, 2019).
breast carcinoma (continued). "Remarkably, expression of KDM4A, the most abundantly expressed gene among KDM4 demethylases in TNBC cell lines was enriched in TNBC compared to other breast cancer subtypes and was positively correlated with FYN expression in CCLE database, suggesting that KDM4 regulates FYN mRNA levels." (PMID 40243589, 2025). "In addition, it has been reported that upregulation of FYN expression in mesothelioma and breast cancer cells stimulates significant resistance to anti-cancer agents by activation of anti-apoptotic and cell-cycle-regulatory proteins." (PMID 39045458, 2024). "Ampelopsins A and C induce cell metastasis by downregulating FYN expression in breast cancer cells." (PMID 36740671, 2023). "miR-381, by inactivation of MAPK signaling via FYN, could induce the sensitivity of breast cancer cells to doxorubicin." (PMID 34804971, 2021). "In addition, FYN protein induces EMT in breast cancer, promoting tumor cell invasion and metastasis." (PMID 33456463, 2020). "Thus, elevated expression and/or activation of FYN is observed in various cancers including glioblastoma, melanoma, squamous cell carcinoma, prostate, and breast cancers, and FYN is an oncoprotein important for cancer cell proliferation and growth." (PMID 32811808, 2020). "Overall, FYN plays a significant role in the pathogenesis of many cancers and varying degrees of evidence link FYN with hepatocellular carcinoma, oral cancer, mesothelioma, breast cancer, chronic myelogenous leukemia, prostate cancer, melanoma, brain cancer, and esophageal squamous cell carcinoma." (PMID 33233470, 2020). "Second, in breast cancer, detection of FYN levels in clinical samples using immunohistochemical techniques (IHC) revealed that FYN expression levels are significantly higher in breast cancer than in adjacent normal tissues and are an important factor in the poor prognosis of breast cancer." (PMID 36740671, 2023). "It was reported to be related to numerous solid tumors, and increased expression of FYN was found to play a promoting role both in cancer occurrence and progression, as well as be a mechanism of resistance to anticancer agents such as breast cancer, and pancreatic cancer." (PMID 33850056, 2021). "The AKT/GSK3β/FYN axis is well-studied for regulating NRF2 nuclear export in non-cancerous, but is poorly understood in cancer, particularly breast cancer." (PMID 39984471, 2025). "Worthy, the signature demonstrated to predict poor outcomes in breast cancer patients exhibiting high transcriptional levels of ITGA11, THBS1, FN1, EMP1, ITGA2, FYN, SPP1, and EMP2." (PMID 38937754, 2024). "High levels of FYN and STAT5 are present in the positive feedback loop between basal breast cancer cells." (PMID 36740671, 2023). "FYN and STAT5 are present at high levels in the positive feedback loop between basal breast cancer cells." (PMID 36740671, 2023). "Additionally, the expression levels of FYN and KDM4A were found to be correlated with poor prognosis in a previously reported breast cancer cohort, highlighting the potential of targeting these two genes as therapeutic targets for TNBC." (PMID 40243589, 2025). "Importantly, MSCs can induce the spread of cancerous cells; Breast cancer cells treated with MSCs showed overexpression of oncogenes (NCOA4, FOS), proto-oncogenes (FYN, JUN), and EMT-specific markers, leading to breast cancer metastasis." (PMID 37849741, 2023). "Although the immunogenicity of FYN has not been experimentally proven, its prognostic impact on a variety of tumors is obvious, such as breast cancer, pancreatic cancer." (PMID 35547260, 2022). "When breast cancer cells were directly co-cultured with MSCs, they demonstrated substantial overexpression of oncogenes (NCOA4, FOS), proto-oncogenes (FYN, JUN), and EMT specific markers, as well as shape and growth pattern changes, resulting in breast cancer metastasis." (PMID 34736460, 2021). "FYN mRNA expression was not induced by hypoxia in two breast cancer cell lines." (PMID 25326682, 2014).